ADGRG3 (adhesion G protein-coupled receptor G3)
Description:
Adhesion G protein-coupled receptor (aGPCR) for glucocorticoid hormones such as cortisol, cortisone and 11-deoxycortisol. Ligand binding causes a conformation change that triggers signaling via guanine nucleotide-binding proteins (G proteins) and modulates the activity of downstream effectors, such as adenylate cyclase. ADGRG3/GPR97 is coupled to G(o)/GNAO1 G proteins and mediates signaling by inhibiting adenylate cyclase activity. May also signal through G-alpha(q)- proteins; additional evidence are however required to confirm this result in vivo. Plays a role in the regulation of various processes including B-cell development, inflammation or innate immunity. Regulates migration of lymphatic endothelial cells in vitro via the small GTPases RhoA and CDC42. Antibody ligation leads to the production and activation of antimicrobial mediators like reactive oxygen species (ROS) and myeloperoxidase (MPO) as well as enhanced bacteria uptake and killing by granulocytes. Additionally, collaborates with protease-activated receptor 2/PAR2 to stimulate neutrophil-driven antimicrobial responses and endothelial cell activation.
Synonyms: GPR97; PGR26; Pb99
Tractability: Small molecule: a structure with a bound ligand is known. Antibody: UniProt places it where antibodies can reach, with high confidence; its Gene Ontology location is reachable by antibodies, with high confidence; UniProt predicts a signal peptide or a membrane-spanning region.
Target class: Family B G protein-coupled receptor; Membrane receptor
Gene: Protein-coding gene on chromosome 16 (57,668,277 to 57,689,378, forward strand). Ensembl gene ENSG00000182885.
Subcellular location: Cell membrane
Pathways (Reactome):
Immune System: Neutrophil degranulation
Gene Ontology:
Molecular function: G protein-coupled receptor activity; protein binding; transmembrane signaling receptor activity
Biological process: adenylate cyclase-inhibiting G protein-coupled receptor signaling pathway; G protein-coupled receptor signaling pathway; regulation of cell migration; B cell differentiation; negative regulation of non-canonical NF-kappaB signal transduction; cell surface receptor signaling pathway
Cellular component: plasma membrane; membrane; specific granule membrane
Genetic constraint (gnomAD): Loss-of-function variants: 38 observed, 53.58 expected, observed/expected ratio (o/e) 0.71, 90% interval 0.55 to 0.93. The upper end of that interval is the gene's LOEUF score, 0.93, which puts it in group 3 of 6, group 1 being the genes least tolerant of losing a copy. Missense variants: 619 observed, 676.12 expected, observed/expected ratio (o/e) 0.92, 90% interval 0.86 to 0.98. Synonymous variants: 294 observed, 283.67 expected, observed/expected ratio (o/e) 1.04, 90% interval 0.94 to 1.14.
Homologues: Orthologues: chimpanzee ADGRG3 (98% identical), macaque ADGRG3 (93% identical), pig ADGRG3 (71% identical), rat Adgrg3 (70% identical), guinea pig ADGRG3 (68% identical), mouse Adgrg3 (68% identical), dog ADGRG3 (68% identical), zebrafish adgrg1 (26% identical). Paralogues in human: ADGRG1 (31% identical), ADGRG5 (28% identical), ADGRG4 (24% identical), ADGRG6 (24% identical), ADGRG2 (24% identical), ADGRL1 (22% identical), ADGRL3 (21% identical), ADGRB1 (21% identical), ADGRL2 (21% identical), ADGRE2 (20% identical), ADGRB2 (20% identical), ADGRB3 (20% identical), and 30 more.
Diseases named in the same sentence as ADGRG3 in open-access papers:
ADGRG3 is named in the same sentence as 37 diseases in open-access papers, as found by Europe PMC text mining. Sharing a sentence is not in itself a finding about the gene and the disease. The quoted sentences say what the papers report.
Obesity (5 papers, 2016 to 2023). Accumulation of substantial excess body fat. "Additionally, WT mice have more severe inflammation caused by obesity than ADGRG3−/− mice." (PMID 36975519, 2023).
Parkinson disease (3 papers, 2013 to 2021). A progressive degenerative disorder of the central nervous system characterized by loss of dopamine producing neurons in the substantia nigra and the presence of Lewy bodies in the substantia nigra and locus coeruleus. "Our findings are in line with reports of enhanced ADGRG3 transcription in PMNs of patients with severe trauma injury as well as in blood cells of Parkinson's disease and type 2 diabetes patients." (PMID 30559745, 2018).
asthma (2 papers, 2015 to 2025). "Studies have shown that ADGRG3 is highly expressed in eosinophils, neutrophils and mast cells, which participates in macrophage inflammation induced by high-fat diet in obese mice and plays a key role in the occurrence and development of asthma." (PMID 40110435, 2025).
silicosis (2 papers, 2022). Silicosis is a respiratory disease caused by breathing in (inhaling) silica dust. "The underlying biological mechanisms by which lncRNA ADGRG3 and rs1814521 regulate the development of silicosis need further study." (PMID 35289324, 2022). "Taken together, we revealed that the variant A allele of rs1814521 located in the lncRNA ADGRG3 was associated with a decreased risk of silicosis." (PMID 35289324, 2022). "The presence of the SNP rs1814521 in the lncRNA ADGRG3 is associated with susceptibility to silicosis." (PMID 35289324, 2022). "Future studies should aim to elucidate the mechanisms underlying the effects of lncRNA ADGRG3 and rs1814521 in silicosis development." (PMID 35289324, 2022). "The functional SNP rs1814521 in lncRNA ADGRG3 could affect the risk of silicosis and ADGRG3 was lowly expressed in silicosis cases." (PMID 35289324, 2022). "In the present study, lncRNA ADGRG3 was found to be significantly downregulated in silicosis cases compared to the healthy controls, indicating that lncRNA ADGRG3 may play a role in the development of silicosis." (PMID 35289324, 2022). "Moreover, ADGRG3 was found to be lowly expressed in silicosis cases." (PMID 35289324, 2022).
keratinocyte carcinoma (1 paper, 2023). A skin cancer arising from the keratin-producing cells of the epidermis. "Using whole exome sequencing data, we performed groupwise tests for rare missense variants in our dataset and found robust associations (p < 10−6, Burden Zeggini test) between MC1R, EPHA8, EPO, MYCT1, ADGRG3, and MGME1 and keratinocyte cancer." (PMID 37444464, 2023).
pulmonary fibrosis (1 paper, 2022). Chronic progressive interstitial lung disorder characterized by the replacement of the lung tissue by connective tissue, leading to progressive dyspnea, respiratory failure, or right heart failure. "Additionally, ADGRG3 has been shown to inhibit NF-κB signaling, whereas activated NF-κB signaling further promotes alveolar epithelial cell senescence, which ultimately leads to pulmonary fibrosis." (PMID 35289324, 2022).
uterine corpus endometrial carcinoma (1 paper, 2025). A endometrial carcinoma (disease) that involves the body of uterus. "Correlation studies of ADGRs reveals that ADGRG3, ADGRA1, ADGRF1, CD4T cells and CD8 cells were involved in the tumor-related inflammatory response of uterine corpus endometrial carcinoma (UCEC) patients, and affected the clinical prognosis of UCEC patients." (PMID 40110435, 2025).
tumor (4 papers, 2015 to 2025). "Several of the genes described here can be assigned to categories that are involved in the development of solid tumors: MC1R is involved in pigmentation/UV protection, EPB41 and MYCT in tumor suppression, and ADGRG3 in immunomodulation." (PMID 37444464, 2023).
ADGRG3 also shares sentences with these, for which no sentence is quoted: acute kidney injury (2 papers); appendicitis (2); cancer (2); experimental autoimmune encephalomyelitis (2); metabolic disorder (2); type 2 diabetes (2); allergic asthma (1); Alzheimer disease (1); Anxiety (1); bacterial sepsis (1); chronic asthma (1); colon cancers (1); congenital heart defects (1); depression (1); diabetes (1); diabetic nephropathy (1); endometriosis (1); epilepsy (1); gastric adenocarcinoma (1); glioma (1); granulomatosis with polyangiitis (1); Hypertension (1); inflammation (1); kidney (1); metabolic syndrome (1); neurodevelopmental disorder (1); polymicrogyria (1); schizophrenia (1); Stroke (1).